HLA-E (major histocompatibility complex, class I, E)
Diseases named in the same sentence as HLA-E in open-access papers (continued):
Sharing a sentence is not in itself a finding about the gene and the disease.
liver disease (1 paper, 2018). "This study aimed to evaluate the expression of HLA-E in the liver and its association with the severity of liver disease in HCV patients." (PMID 29951556, 2018). "Human leukocyte antigen E (HLA-E) might regulate the antiviral function of immune response and contribute to the persistence of HCV and the severity of liver disease." (PMID 29951556, 2018).
lymph node metastasis (1 paper, 2024). "The results indicated that elevated HLA-E levels (IRS ≥ 6) are associated with lymph node metastasis in ESCC and are predictive of both the cumulative incidence of recurrence (CIR) and tumor-related death (CID)." (PMID 39845968, 2024).
malaria (1 paper, 2025). Malaria is a serious and sometimes fatal disease caused by a parasite that commonly infects a certain type of mosquito which feeds on humans. "The widespread cross-reactivity of malaria epitopes recognized by Pv-infected donors likely is due in part to the pauciclonality of functional HLA-E alleles in human populations." (PMID 40502747, 2025). "Thus, we asked if our screened malaria peptides could be presented by HLA-E." (PMID 40502747, 2025).
meningioma (1 paper, 2020). A generally slow growing tumor attached to the dura mater. "If this were true, however, we would expect to see less immunosuppressive action for HLA-E, with a decrease in the incidence of meningiomas in older adults." (PMID 32903787, 2020). "Primary and recurrent meningiomas showed no significant relation with HLA-E and hormone receptors (p > 0.05), except for Ki67, where a higher median was observed in recurrent tumors than in primary (p = 0.014)." (PMID 32903787, 2020).
Merkel cell carcinoma (1 paper, 2023). "It was found that HLA-E was more frequently expressed than PD-L1 in several types of cancer, including Merkel cell carcinoma, and, additionally, the in vivo CRISPR screening knock-out of Qa1b led to the increased efficacy of immunotherapy by PD-1 blockade." (PMID 36829496, 2023).
metastatic melanoma (1 paper, 2023). A melanoma that has spread from its primary site to another anatomic site. "In addition, the Kaplan-Meier survival analysis further revealed that the high-expression groups of HLA-C, HLA-E, and HLA-F had a longer survival time among patients with metastatic melanoma." (PMID 37435067, 2023).
oligodendroglioma (1 paper, 2020). A well-differentiated (WHO grade II), diffusely infiltrating neuroglial tumor, typically located in the cerebral hemispheres. "As for patients with oligodendrogliomas, low HLA-E expression remained to be associated with improved PFS (p = 0.026, Log-rank test) and OS (p = 0.028, Log-rank test)." (PMID 32066399, 2020). "Accordingly, immunotherapy may show better efficacy on LGG patients with low HLA-E expression, especially for those with oligodendrogliomas." (PMID 32066399, 2020).
pleural cancer (1 paper, 2025). A primary or metastatic malignant neoplasm affecting the pleura. "Analysis of 11 antigens that regulated NK cell activity in pleural cancer revealed that HLA-E and HLA-C were the predominant tumor-associated antigens." (PMID 40959273, 2025). "In our study, we found that metastatic pleural cancer cells with high expression of HLA-E exhibited a senescence phenotype." (PMID 40959273, 2025).
pulmonary TB (1 paper, 2015). "Moreover, patients with pulmonary TB had such ‘Th2-like’ non classical CD8+ T-cells in their circulation as visualised using specific Mtb peptide/HLA-E tetramers." (PMID 25803478, 2015).
spontaneous abortion (1 paper, 2016). Expulsion of the product of FERTILIZATION before completing the term of GESTATION and without deliberate interference. "This study was designated to investigate the gene frequencies of E0101 and E0103 in HLA-E gene in Iranian women with recurrent spontaneous abortion (RSA)." (PMID 27525333, 2016).
Stevens-Johnson syndrome (1 paper, 2018). Stevens-Johnson syndrome is a limited form of toxic epidermal necrolysis characterized by destruction and detachment of the skin epithelium and mucous membranes involving less than 10% of the body surface area. "HLA-E expression has not been previously associated with PV skin, but keratinocytes near blisters in Stevens Johnson's Syndrome have been shown to increase expression of HLA-E, which enhances the chances of cell death by NK T cells, who require the atypical class I HLA-E molecule to be primed." (PMID 30155465, 2018).
vitiligo (1 paper, 2013). Generalized well circumscribed patches of leukoderma that are generally distributed over symmetric body locations and is due to autoimmune destruction of melanocytes. "The DDR1 gene is located between the HLA-E and HLA-C genes at chromosomal region 6p21, previously linked to vitiligo susceptibility in a Chinese population." (PMID 24385829, 2013).
ZIKV infection (1 paper, 2025). "During acute ZIKV infection, circulating PMBCs had increased expression of HLA-C and HLA-E, suggesting a potential for NK cell inhibition, similar to what we found in acute DENV." (PMID 41000887, 2025). "We found that increased expression of NK inhibitory receptors HLA class I (Pan-HLA; HLA-C, HLA-E) and CD95 (Fas) are predictive of acute ZIKV infection vs. healthy across multiple cell types." (PMID 41000887, 2025).
tumor (310 papers, 2009 to 2026). "HLA-E expression in tumor cells can be regulated in response to immune associated factors such as IFNγ, TNFα, IL-1β and IL-27, which are also associated to GMM educated immune cells." (PMID 39229258, 2024). "Due to their binding to the inhibitory CD94/NKG2A receptor, Qa-1 and HLA-E are associated with tumor immune evasion." (PMID 39424778, 2024). "Growing evidence suggests that HLA-E molecules present pathogen-derived and tumor-associated peptides to CD8+ T cells, positioning them as promising targets for universal immunotherapies due to their minimal polymorphism." (PMID 39301027, 2024). "The use of monalizumab was associated with high levels of HLA-E in primary tumour cells obtained from four patients with HNSCC." (PMID 36980527, 2023). "To determine the influence of the level of HLA‐E surface expression on the malignant cells, we inoculated HLA‐Elow (non‐transfected) and HLA‐Ehigh (transfected) Cal‐27 tumor‐cell variants on opposite flanks of Rag2−/‐IL2Rγ−/− mice." (PMID 37782273, 2023). "Low level of tumor-mutation burden and high expression level of HLA-E significantly reduced progression-free survival." (PMID 35530307, 2022). "High expression of HLA-E by tumour cells, tumour-associated macrophages and dendritic cells can limit the anti-tumour immune response by NKG2A+ CD8+ tumour-infiltrating lymphocytes." (PMID 36560403, 2022). "Selenium derivatives can suppress the expression of HLA-E in tumor cells, thereby making them susceptible to natural killer cells, which leads to tumor-cell death." (PMID 34885879, 2021). "This is illustrated by HLA-E upregulation on tumor cells upon spheroid infiltration, associated with NKG2A increase in infiltrating immune cells." (PMID 33096896, 2020). "While HLA-E surface expression in tumor cells is very weak, IFN-γ produced by NK cells can cause its overexpression." (PMID 33391277, 2020). "This is illustrated by HLA-E upregulation on tumor cells upon spheroid infiltration, associated with NKG2A increase on infiltrating immune cells." (PMID 30871626, 2019). "The NK/CD8+ T cell cytotoxic capability is lost when tumor-associated human leukocyte antigen, HLA-E, binds the CD94/NKG2A receptor, resulting in tumor progression and reduced survival." (PMID 31009335, 2019). "Treatment of tumor cells with selenite has been shown to result in loss of HLA-E expression thereby increasing susceptibility to CD94/NKG2A-positive natural killer (NK) cells mediated tumor cell killing." (PMID 30324091, 2018). "In the major mechanism underlying tumor immune escape, HLA-E binds to the leading peptides of HLA-A, -B, -C, and -G, activating the CD94/NKG2A receptor and delivering an inhibitory signal to NK and CTL cells." (PMID 27322426, 2016). "To investigate the prognostic value of CD8+ tumor infiltrating T cells in the context of HLA-A, B and C as well as HLA-E and its association with OS, we retrospectively studied a group of 197 patients with NSCLC." (PMID 26658106, 2016). "The underlying mechanism of HLA-E-mediated promotion of tumor progression was studied recently at the molecular level." (PMID 27322426, 2016). "This high expression of HLA-E was associated with tumor stage and N-myc gene status, which definitively correlated with prognosis." (PMID 27322426, 2016). "In colorectal cancer patients, tumor expression of HLA-E is associated with shorter disease-free survival time." (PMID 26697006, 2015). "This overexpression of HLA-E is proposed to be associated with the inhibition of tumor tissue infiltrating NK or CD94+/NKG2A+/CD8+ T cells, resulting as a poor prognosis marker." (PMID 25401109, 2014). "For this, the identification and functional assessment of tumor specific peptides presented by HLA-E and the presumable differences in the peptide repertoire of the two functional HLA-E alleles are of high importance." (PMID 25401109, 2014).
tumor (continued). "It is clear from our data that nanoparticles containing class Ib MHC (Qa-1 or HLA-E in humans) binding tumor-associated antigens can also be designed." (PMID 21450109, 2011). "We further investigated the underlying mechanism for HLA-E expression in tumor cells." (PMID 40959273, 2025). "Moreover, understanding the underlying mechanisms of immune evasion and the role of HLA-E in different tumor microenvironments is crucial for developing effective treatments." (PMID 40066089, 2025). "However, in BC, elevated tumor expression of HLA-E is associated with increased disease progression, revealing the inhibitory role of the NKG2A/HLA-E interaction." (PMID 39857739, 2025). "However, in patient 1, the decreased expression of the peptide presenting HLA alleles (HLA-A, -B, and -C) and HLA-E was accompanied by a notably increased infiltration of NK cells into the tumor." (PMID 38281021, 2024). "Furthermore, the expression of CD94/NKG2A in the immune cells and/or their ligand HLA-E in the tumor cells is also regulated by gut microbiota associated immune factors." (PMID 39229258, 2024). "Furthermore, we discovered that overexpressing HLA‐E can counteract the tumor‐promoting effects of IRF5‐deficient M1‐like macrophage exosomes." (PMID 39623605, 2024). "These examples demonstrate that upregulation of HLA-E on tumor or virally infected cells might be associated with a decreased immune response." (PMID 38069020, 2023). "Genetic variations in HLA-E alleles can influence their role in tumor immunosurveillance." (PMID 38067396, 2023). "The influence of HLA‐E tumor expression levels in susceptibility to treatment may suggest its value as a biomarker." (PMID 37782273, 2023). "HLA-E has been associated with the genesis of various tumor types in recent years." (PMID 38069020, 2023). "However, it is still unclear how the HLA-E*0103 allele is preferentially expressed in EOC tumor cells and how both alleles are affected and regulated during tumor development." (PMID 38067396, 2023). "Among these, NKG2A could be a relevant candidate target due to its overexpression in about 15% of CD8+ TILs in CRC (often associated with HLA-E) and its strong impact on inhibiting anti-tumor T responses." (PMID 36077799, 2022). "Indeed, the vaccination with autologous tumor cells augmented the MFIs of HLA-E and several other HLA-Ia alleles." (PMID 35323192, 2022). "HRD profile was associated with high HLA-E expression on tumor cells and an improved OS." (PMID 35267497, 2022). "Expression of KLRC1 gene, which encodes NKG2A, was found to correlate with HLA-E in tumor samples." (PMID 33671917, 2021). "Thus, HLA-E is common in EwS and is associated with T cell infiltration, both in human patients and in murine xenografts treated with tumor-antigen specific CART." (PMID 34201079, 2021). "Additionally, our analysis also identified that the expression pattern of HLA-E was also associated with the origin of tumor cells." (PMID 32066399, 2020). "HLA-E overexpression has been shown to negatively interfere with innate immune responses thereby protecting cells from susceptibility to lysis, which resulted in resistance of HLA-E+ tumor cells to NK cell-mediated cytotoxicity." (PMID 27589686, 2016). "Moreover, a better relapse-free survival was associated with a low HLA-G expression and with a high HLA-E expression, thus suggesting a divergent role of these molecules in the progression of this type of tumor." (PMID 25202308, 2014). "The emerging role of HLA-E in CD8+ T cell activation has recently increased interest in developing universal vaccination and T-cell-based immunotherapy strategies targeting HLA-E-bound viral or tumor-associated epitopes that may be shared across all individuals." (PMID 39301027, 2024).
tumor (continued). "Finally, in HLA-E+ tumors, expressing tumor-associated antigens, NKG2A blockade could increase the therapeutic efficacy of other mAbs (for example, anti-EGFR mAb), favoring the NK cell triggering via the CD16-mediated antibody-dependent cytotoxicity (ADCC)." (PMID 32010130, 2019). "In addition to immune escape, HLA-E may promote tumor growth via other mechanisms related to tumor stem cell differentiation, tumor-associated macrophage activity, and functional activation of the vascular endothelium." (PMID 27322426, 2016). "Several high-scoring proteins, including ITGB8, LGR5, FZD7, HLA-E, ANGPTL2, and BST2 emerged as candidates potentially affected by protonation-linked perturbations in acidic tumor microenvironments." (PMID 42036641, 2026). "Transcriptomic analyses of tumor cells surviving CAR-NK exposure revealed inflammatory activation with progressive HLA-E upregulation, which impaired CAR-NK function." (PMID 41845478, 2026). "While these HCMV-specific mechanisms involve viral proteins, tumours can also upregulate HLA-E expression through alternative pathways." (PMID 41463341, 2025). "As such, the NKG2A:HLA-E inhibitory axis is a significant pathway exploited by tumours to evade NK cell-mediated immunity." (PMID 40291981, 2025). "High expression of HLA-E by tumor cells, TAM and dendritic cells can dampen the anti-tumor immune response of tumor-infiltrating CD8 T cells and NK cells, activating the inhibitory axis NKG2A/HLA-E." (PMID 40433358, 2025). "The limited amount of HLA-E on the surface of normal cells helps them avoid an autoimmune reaction; however, in tumor cells, the cytotoxicity of NK cells is inhibited due to an increase in HLA-E." (PMID 41369346, 2025). "Tumor cells upregulate inhibitory ligands such as HLA-E, HLA-G, and PD-L1, which interact with NKG2A, KIRs, and PD-1, leading to profound suppression of NK cells cytotoxicity." (PMID 41562080, 2025). "Studies have shown that NKG2A is expressed on both NK cells and T cells in various tumors, with its ligand HLA-E frequently overexpressed in tumor cells." (PMID 40370819, 2025). "We demonstrate that senescent cancer cells upregulate HLA-E, which directly impairs NK cell cytotoxicity and suppresses cDC1 recruitment, thereby weakening innate and adaptive anti-tumor immunity." (PMID 40959273, 2025). "Circulating tumor cells can enhance HLA-E expression and bind to CD94 (KLRD1)/NKG2A on NK cells, thereby weakening NK-mediated tumor cell killing and cDC1 recruitment via XCL2 secretion." (PMID 40959273, 2025). "These dynamics highlight the importance of upstream immune signalling pathways that regulate MHC and HLA-E expression, including cytokines involved in anti-tumour responses." (PMID 41463341, 2025). "In certain tumors, HLA-E expression can diminish the protective role of tumor-infiltrating lymphocytes, thus contributing to immune escape." (PMID 40066089, 2025). "HLA-E expression levels, typically elevated in tumor cells compared to healthy tissues, lead to the inhibition of cytotoxic NK cells and CD8 T lymphocytes through interaction with the NKG2A/CD94 heterodimer." (PMID 40066089, 2025). "Studies have demonstrated that blocking the KLRC1/HLA-E pathway in PC significantly enhances the anti-tumor activity of effector cells, thereby suppressing tumor progression." (PMID 40486509, 2025). "NKG2x receptors can shape the functional status of NK cells by signalling through the NKG2A (inhibitory) or NKG2C/NKG2E (activating) receptors when they engage HLA-E presented by tumour cells." (PMID 40361496, 2025). "In PF, nearly all tumor cells expressed both HLA-I and HLA-E, confirming their widespread presence in this compartment." (PMID 40877861, 2025). "Tumor cells and stromal components upregulate inhibitory ligands including HLA-E/HLA-G and PD-L1, thereby suppressing NK cells cytotoxicity." (PMID 41562080, 2025). "HLA-E has shown significant therapeutic potential due to its expression in tumor cells compared to healthy tissues." (PMID 40066089, 2025).